SNORD114-31 (small nucleolar RNA, C/D box 114-31)
Synonyms: 14q(II-31)
Gene: Small nucleolar RNA gene on chromosome 14 (100,993,236 to 100,993,310, forward strand). Ensembl gene ENSG00000200089.
Gene Ontology:
Biological process: RNA processing
Cellular component: nucleolus
Homologues: Orthologues: chimpanzee SNORD114-31 (100% identical), macaque SNORD114-31 (89% identical). Paralogues in human: SNORD114-3 (80% identical), SNORD114-11 (76% identical), SNORD114-4 (76% identical), SNORD114-12 (73% identical), SNORD114-14 (73% identical), SNORD114-17 (73% identical), SNORD114-13 (72% identical), SNORD114-21 (72% identical), SNORD114-23 (72% identical), SNORD114-9 (72% identical), SNORD114-18 (71% identical), SNORD114-22 (71% identical), and 26 more.